ICAM1 (intercellular adhesion molecule 1)
Diseases named in the same sentence as ICAM1 in open-access papers (continued):
Sharing a sentence is not in itself a finding about the gene and the disease.
tumor (continued). "For ICAM1, IGSF4, EHM2, CLDN1 and MUC1, no methylation was detected in 20 sporadic RCC tumours." (PMID 18195710, 2008). "Although direct co-localisation with endothelial markers was not assessed, the higher expression of ICAM-1 and VCAM-1 observed in tumour tissues relative to cultured cancer cells suggests that stromal and endothelial cells likely contribute to their expression within the tumour microenvironment." (PMID 41228228, 2025). "Icam-1/CD54 and Timp1 levels, which showed difference in pancreas tissues from GEM mice, were either undetectable or comparable in CM from KPC sgSC and KPC sgUlk1 cells, suggesting that these factors probably originate from stromal fibroblasts rather than from tumor epithelial cells." (PMID 41408407, 2025). "In addition to tumor cell producing or leaky blood vessel deposited FGG, other non-tumor cell expressing FGG may also participate in ICAM-1‒FGG mediated NSCLC cell survival." (PMID 39168965, 2024). "Mechanistically, we demonstrated that the anergic state of tumor endothelial cells is not an epiphenomenon of the proliferative state of the cells, as two anti-proliferative drugs, i.e. imatinib and BEZ-235, were found not to normalize endothelial ICAM-1 expression." (PMID 36459240, 2023). "Tumor growth was not altered by transfection, but mRNA levels of vascular endothelial growth factor (VEGF) and intercellular adhesion molecule - 1 precursor (ICAM-1) - were reduced and this aspect correlated with the malignancy and the metastatic potential of OS." (PMID 29304852, 2018). "Therefore, the effect of microgravity on ICAM-1 in cells of the MMS is not consistent, which could be the consequence of different cell systems (tumor cell models in various states of differentiation versus primary cells) and experiment times." (PMID 28419128, 2017). "Interestingly, while monocytes and neutrophils are also typically recruited via adhesion molecules such as P-selectin, E-selectin, ICAM-1 and VCAM-1, the downregulation of these endothelial molecules in tumours does not appear to correlate with decreased monocyte or neutrophil infiltration." (PMID 28435677, 2017). "Pretreating tumor-cell targets with mL4-3 and L1-7(N) significantly increased lysis of OV17-1 cultures by CEA-specific T cells (from 29 to 74 %), while the addition of an anti-ICAM-1 blocking antibody, but not the corresponding isotype control, significantly reduced lysis (from 74 to 40 %)." (PMID 26579226, 2015). "Although ICAM-1 expression was not modulated following hyperthermia in vitro, it was significantly upregulated after exposure to both ultra low (7 s) and low (30 s) doses of RFA in vivo, which suggests a role for the tumor microenvironment in ICAM-1 regulation, in agreement with other reports." (PMID 23894654, 2013). "Furthermore, canonical vascular adhesion molecules recognized by the CTLs like ICAM-1 and VCAM-1 were not upregulated nearby the lung-residing intravascular E0771 cells as a potential means to recruit lung circulating CTLs to the vicinity of the intravascular tumor cells." (PMID 41660608, 2026).
cancer (649 papers, 1993 to 2026). A tumor composed of atypical neoplastic, often pleomorphic cells that invade other tissues. "Lymphocyte function-associated antigen 1(LFA-1) and Intercellular adhesion molecule-1 (ICAM-1) integrin engagement has been shown to be important in the formation of natural killer cell immunological synapses with cancer cells." (PMID 41039118, 2025). "Among them, only ICAM1 was identified by Kaplan–Meier analysis as being associated with reduced cancer recurrence." (PMID 39590296, 2024). "Further research is warranted to elucidate the mechanisms underlying these associations and to harness ICAM1’s potential in cancer therapy." (PMID 39767561, 2024). "A similar pattern was reported for colon and bladder cancer: expression of ICAM-1 is associated with invasiveness and poor prognosis." (PMID 39335111, 2024). "Intercellular adhesion molecule (ICAM) 1 is a transmembrane protein found in various cancer cells and is associated with the spread of cancer and poor prognosis." (PMID 39132161, 2024). "Clinical data establish an inverse association between the NSCLC patients overall survival and cancer expression of intercellular adhesion molecule-1 (ICAM-1), a transmembrane glycoprotein belonging to the immunoglobulin (Ig) superfamily of adhesion molecules." (PMID 39168965, 2024). "Further discovery proves that CDK4/6 inhibitors upregulate ICAM1 transcription by inhibiting phosphorylation of retinoblastoma protein RB in LKB1 deficient cancer cells." (PMID 36871040, 2023). "In this study, we identified the cell membrane protein intercellular adhesion molecule-1 (ICAM1) as a potential molecular therapeutic target for CCA by screening a panel of cancer-associated surface antigens in combination with clinical data." (PMID 37717087, 2023). "Clinical studies have demonstrated that upregulation of ICAM‐1 in the TME is associated with a good prognosis for patients with various cancers, suggesting enhanced immune surveillance of cancer." (PMID 37638340, 2023). "To understand the role of common mutations in developing drug targets, we analyzed common ICAM1 mutation types in various cancers using cBioPortal datasets." (PMID 37671167, 2023). "One previous study reported that the high migration ability of cancer is associated with the overexpression of ICAM-1." (PMID 37575276, 2023). "ICAM-1 expression is dysregulated in many cancers, and polymorphisms in the ICAM1 gene implicate the molecule in cancer susceptibility." (PMID 37237555, 2023). "Intercellular Adhesion Molecule 1 (ICAM1) is responsible for T cell tumor infiltration, and therefore a variation in this gene can increase cancer susceptibility, as shown for rs5498 in the Taiwanese population." (PMID 38025894, 2023). "Among the proteins exhibiting a decrease, ICAM-1 (encoded by Icam1) represents an adhesive molecule also known to weaken the immune response in cancer cells in addition to its promoting action on cancer progression." (PMID 36430209, 2022). "In a meta-analysis of 18 case-control studies, ICAM-1 polymorphism was linked to cancer risk, similar to a meta-analysis of 12 case-control studies on T2D and CHD in a meta-analysis of 11 case-control studies." (PMID 33803155, 2021). "ICAM1 facilitates intercellular interactions between cells and is implicated in promoting the invasiveness and metastatic ability of cancers." (PMID 32899628, 2020). "The underlying mechanism is thought to include upregulation of ICAM-1 (intercellular adhesion molecule 1) on the surface of cancer cells by cannabinoids leading to crosslink with the related lymphocyte function antigen-1 on the surface of killer cells." (PMID 32839414, 2020). "NK cell-derived IFN-γ can also improve cancer cell recognition and associated NK cell cytotoxicity through ICAM-1 upregulation on cancer cells." (PMID 33322371, 2020).
cancer (continued). "First, intercellular adhesion molecule-1 (ICAM-1) and vascular cell adhesion molecule-1 (VCAM-1) are needed for the extravasation of T cells and upregulation of ICAM-1 has been associated with good prognosis of cancer patients." (PMID 33614478, 2020). "By establishing a mouse xenograft model, we found that ICAM1-specific CAR-T caused regression of established cancer and prolonged survival." (PMID 33072116, 2020). "Herein, we show that the NANOG-mediated repression of ICAM1 is a critical mechanism underlying the ability of cancer cells to escape natural killer (NK) cell attack during the initial stage of prostate cancer (PCa) formation." (PMID 31619256, 2019). "We have here identified ICAM-1 which reciprocally regulated by AF1q was associated with metastasis of cancer cells." (PMID 31297450, 2019). "In agreement with the literature, our own work suggested that ICAM-1 is a biomarker associated with cancer progression." (PMID 30470940, 2019). "As ICAM1 is directly associated with cell migration, this provides a mechanistic link between metformin and abrogation of cancer cell invasiveness." (PMID 30469399, 2018). "The association of ICAM-1 with invasion and metastases has been demonstrated in several types of cancer." (PMID 29228586, 2017). "Celecoxib enhanced the susceptibility of cancer cells to be lysed by LAK cells with the respective effect being reversed by a neutralizing ICAM-1 antibody." (PMID 26513172, 2015). "Previous studies have shown that CXCR4, VEGF, TGF-β, ICAM-1 are associated with various roles of macrophages during the process of carcinoma invasion and metastasis." (PMID 25434400, 2015). "We recently reported that miR-222 and -339 in cancer cells down-regulate the expression of an intercellular cell adhesion molecule (ICAM)-1, thereby regulating the susceptibility of cancer cells to cytotoxic T lymphocytes (CTLs)." (PMID 20167088, 2010). "The aqueous extract of Picralima nitida, particularly in conjunction with Cymbopogon citratus, altered the expression of GSK3β and Intercellular Adhesion Molecule-1 (ICAM-1), both of which are linked to the development of cancer and the control of the immune system." (PMID 40735234, 2025). "Additionally, the combinational treatment led to the upregulation of gene encoding ICAM1/2, the cell adhesion molecules, which activate PLCγ, a component of the Ca signalling pathway, facilitating the recognition of cancer cells by NK cells." (PMID 38674023, 2024). "However, engineered CAR-NK cells have been described to overcome cancer cell resistance caused by ICAM-1 reduction because the CAR-mediated killing by NK-92/5.28.z cells used in this study is ICAM-1 independent." (PMID 39596815, 2024). "These ligands in particular are such as those involved in the context of adhesion molecules expressed on CD133+/− (CXCR4-) medullablastoma cancer stem cells (HTB-186 that expressed ICAM-1, VCAM-1, LFA-3), susceptible to natural killer (NK) cell mediated activity-killing." (PMID 38155835, 2023). "Additionally, ICAM1 shows an increased expression in various types of cancer, being associated with advanced disease stages of the disease, chemotherapy resistance, and lower survival." (PMID 37628945, 2023). "Furthermore, the LFA-1/ICAM-1 complex has been found to be associated with the growth and metastasis of various cancers." (PMID 37388230, 2023). "This provoked us to seek regulatory mechanism of ICAM1 in LKB1 deficient cancer cells." (PMID 36871040, 2023). "ICAM-1 has been found to be upregulated in many cancers and has been implicated in carcinogenesis." (PMID 35871446, 2023). "As ICAM-1 upregulation has been connected to various types of cancer and might promote cancer metastasis, a causative link between BILF1 expression and ICAM-1 upregulation may be valuable to elucidate mechanisms of EBV oncogenicity." (PMID 34439235, 2021). "The adhesion molecule ICAM-1 is associated with different cancer types." (PMID 34445479, 2021).
cancer (continued). "Additionally, the expression of ICAM-1 has been observed in various types of cancers and is associated with advanced cancer stages." (PMID 35056985, 2021). "ICAM1 has been reported to associated with cancer metastasis, including PC." (PMID 33128857, 2020). "Additionally, expression of ICAM-1 has been observed in various types of cancers and is associated with advanced cancer stages; malignant phenotypes of breast, lung, and prostate cancers; and resistance to chemotherapy." (PMID 29137327, 2017). "Since ICAM-1 is an important adhesion molecule playing a key role in leukocyte extravasation during states of inflammation, it was also associated with metastatic progression of cancer." (PMID 29100408, 2017). "However, ICAM1 has been implicated in the metastatic spread of cancer cells." (PMID 37671167, 2023). "A literature review revealed that ICAM-1 plays a crucial role in regulating cell migration in various cell types, including cancer cells, monocytes, and endothelial cells 21-23." (PMID 41399375, 2026). "NK cell–produced TNFα and IFNγ induce ICAM-1 upregulation on K562 cancer cells, which then enhances the cytotoxicity of cancer cells by promoting their conjugate formation with NK cells." (PMID 41128663, 2025). "ICAM1 takes a part in the metastasis of some cancers and declines the immune response in cancer cells." (PMID 39820173, 2025). "More generally, ICAM-1 is reported as a prognostic cancer marker in oral cancer but also breast, colorectal and gastric cancer." (PMID 40071851, 2025). "For example, F. nucleatum has been shown to facilitate cancer cell adhesion to vascular endothelial cells and promote extravasation by upregulating intercellular adhesion molecule 1 (ICAM-1) on CRC cells via activation of the NF-κB signaling pathway." (PMID 40437288, 2025). "Interactions between immune cells and cancer cells through ICAM-1 are also responsible for intratumoral retention of activated CD8+ T-cells." (PMID 40071851, 2025). "A further obstacle is represented by the ability of cancer cells to downregulate ICAM-1 expression as a strategy for immune evasion, thus diminishing the immune-mediated cytotoxicity." (PMID 40597436, 2025). "P-selectin, β-2 microglobulin, ICAM-1, and lumican have been extensively investigated in relation to various types of cancer [,38]." (PMID 41031136, 2025). "ICAM1, a key molecule in cell adhesion and immune cell migration, is upregulated by NF-κB binding to its promoter in cancer cells." (PMID 39576886, 2025). "Our previous work demonstrated that ICAM1 promotes cancer stemness and homotypic CTC cluster formation." (PMID 40955669, 2025). "This phenomenon has been highlighted as the suppression of ICAM-1 expression led to a decrease in cancer cell migration." (PMID 40071851, 2025). "The relationship between ICAM-1 and lumican and cancer appears to be variable, depending on the specific type and stage of cancer [,38]." (PMID 41031136, 2025). "CVA21, a naturally occurring enterovirus most commonly associated with the common cold, finds an ideal receptor complex on the surface of cancer cells when both ICAM-1 and DAF are overexpressed." (PMID 41313526, 2025). "Mechanistically, Notch1 overexpression upregulates the expression of transcriptional factor YY1 (Yin-Yang 1), which in turn represses ICAM1 expression to prohibit CD8+ T cell-derived granzyme-driven cancer cell pyroptosis and cytotoxicity." (PMID 41271562, 2025). "To quantify these dynamics, we exploited an elastic polydimethylsiloxane (PDMS) micropillar array substrate functionalized with CD19 antigen and intercellular adhesion molecule 1 (ICAM-1), mimicking the cancer cell surface while serving as mechanical sensors." (PMID 41282104, 2025). "The interactions between lymphocyte function-associated antigen 1 (LFA-1) and intercellular adhesion molecule-1 (ICAM-1) enable CTLs to infiltrate tumors, recognize cancer cells via T cell receptors, and induce cell death." (PMID 40843361, 2025).
cancer (continued). "To further validate the functionality of the endothelium and examine the effect of cancer cells on endothelial activation, we investigated ICAM‐1 expression following PMA treatment under different culture conditions." (PMID 40223399, 2025). "Another study demonstrated that the downregulation of intracellular adhesion molecule 1 (ICAM-1) enabled HER2-expressing cancer cells to escape the ADCC effect." (PMID 39519282, 2024). "ICAM-1/CD54 is constitutively expressed at relatively low levels on the endothelium, leukocytes, and many other cell types (including cancer cells), but its expression is dramatically increased by multiple inflammatory stimuli, including TNFα, IFN-γ, and IL-1." (PMID 38542421, 2024). "We performed a comprehensive analysis using data from the TCGA database to assess the expression level of ICAM-1 in various cancer types." (PMID 38799250, 2024). "There are also several reports showing an increase in ICAM-1 expression in cancer cells after treatment with pharmacological agents or experimental approaches, thus providing a clue to the enhancement of oncolysis." (PMID 39335111, 2024). "On the other hand, ICAM-1 up-regulation has been often correlated with cancer progression, invasion, and immune escape, as in the case of gastric, colorectal, thyroid, and melanoma cancers." (PMID 39596815, 2024). "Patients receiving TILs with lower ICAM1 expression showed significantly longer OS, implying its clinical relevance in cancer immunotherapy." (PMID 38490212, 2024). "Interactions between cancer cells and Fg, particularly in cases where cancer cells express ICAM-1, expedite endothelial penetration for metastasis by forming Fg-dependent bridges." (PMID 38779081, 2024). "To date, most of the studies on the role of ICAM-1 in cancer focus on cancer-related immune responses and metastasis, little is known about its intrinsic roles on malignant cell growth." (PMID 39168965, 2024). "We observed that the M2-like TAMs upregulated the expression of CD24, CD47 and ICAM1 (markers enriched in cluster C6 cancer cells) in MHCC7L HCC cells." (PMID 38169544, 2024). "These in vivo data reinforce the mechanism that ICAM-1 supports NSCLC cell survival via interacting with cancer cell-derived FGG." (PMID 39168965, 2024). "These CARs specifically lyse cancer cells with high ICAM-1 expression while sparing normal tissues that express basal levels of ICAM-1." (PMID 39397869, 2024). "Then by using ICAM-1 adhesion assay, we found that cancer cell-derived conditioned medium from Bcl6 knockout group increased T cell adhesion to ICAM-1 coated plate compared to wild type cancer medium." (PMID 38956432, 2024). "Similar to these findings, others have also shown WISP1-mediated upregulation of VCAM1 and ICAM1 are crucial for cancer cell migration, invasion, and wound healing." (PMID 39682753, 2024). "Our study has unraveled a unique association between LGMN/SPP1+ TAMs and stemness-related cancer cells (cancer cell cluster C6 marked by co-expression of CD24, CD47 and ICAM1)." (PMID 38169544, 2024). "ICAM-1 functions in multiple steps of the cancer immune cycle, and its expression on DCs collaborates with the surface receptor LFA-1 on T cells to facilitate antigen presentation." (PMID 38169608, 2024). "At clinical stages, alongside with B7.1 and LFA-3, ICAM-1 is one of the TRI-COM costimulatory molecules which have been used as T cell response boosters in vaccines against different types of cancer in combination with other treatments or antigens." (PMID 38542421, 2024). "This process is further facilitated by the presence of TNF-α, another cytokine that is often upregulated in cancer and can synergize with IL-6 to enhance ICAM-1 expression." (PMID 38689325, 2024). "In this regard, recent studies have shown that posttranslational N-myristoylation of ICAM-1 on D1 (Gly23) increases adhesion but reduces the migration of cancer cells." (PMID 38391953, 2024).